HRAS (HRas proto-oncogene, GTPase)
Diseases named in the same sentence as HRAS in open-access papers (continued):
Sharing a sentence is not in itself a finding about the gene and the disease.
tumor (continued). "In HRAS-mutant cell lines, tipifarnib reduced two-dimensional and three-dimensional cell growth, and in vivo treatment with tipifarnib resulted in tumor growth inhibition exclusively in HRAS-mutant RMS xenografts." (PMID 35459782, 2022). "This was evidenced by inhibition of HRAS prenylation in rodent cells, or inhibition of HRAS farnesylation in human tumor cells, which increased their radiosensitization." (PMID 35359456, 2022). "Functional analysis demonstrated that in cooperation with driver genes such as HRAS, it promoted migration, invasion, and anchorage-independent growth in mammalian epithelial cells and promoted tumor formation in vivo." (PMID 34680332, 2021). "Mutations which activate members of the RAS family (KRAS, HRAS, and NRAS) can be found in as much as 20–30% of all human tumours." (PMID 33925206, 2021). "This research was aimed at analyzing the relative levels of KRAS and HRAS genes mRNA expression in whole blood samples in parallel with tumor tissue and, what is an innovative approach, at three points of time during the patients’ observation." (PMID 33549031, 2021). "The translational potential of this combination is strengthened by the growing identification of oncogenic mutations in HRAS, KRAS (HGNC IDs 5173, 6407), NRAS and BRAF (HGNC ID 1097) genes in SS cell lines and clinical tumor subsets." (PMID 34857011, 2021). "This research was aimed at considering the potential clinical usefulness KRAS and HRAS gene as tumor markers playing a role in the diagnosis (the differentiation between malignant and benign disease or histological subtype) as well as predictive biomarkers." (PMID 33549031, 2021). "Our results indicated that miR-1184 promotes tumor progression by directly targeting KRAS/NRAS/HRAS in UBC." (PMID 34234808, 2021). "The median KRAS mRNA expression in tumor tissue obtained during surgery was 0.892 (range, 0.063–12.918), while the median HRAS mRNA expression was 0.978 (range, 0.054–24.194)." (PMID 33549031, 2021). "Collectively, these findings highlight mutant HRAS as a targetable oncogene that can be inhibited by tipifarnib, resulting in either consistent stasis or tumor regression in vivo in multiple preclinical models." (PMID 34771475, 2021). "The therapeutic index of pan-RAS inhibitors will depend on the effects of targeting mutant RAS (KRAS, HRAS or NRAS) oncogene addiction in tumour cells compared to the effect on normal cells when activated RAS is inhibited." (PMID 33462327, 2021). "Tipifarnib (HRAS inhibitor) and palbociclib (cyclin D-cyclin-dependent kinase 4/6 inhibitor), both also currently being investigated, have shown reduction in tumour size." (PMID 34062862, 2021). "The investigators also demonstrated that tipifarnib induced selective anti-tumor activity, with HRAS wild-type tumors growing progressively on tipifarnib treatment but HRAS mutant tumors being highly sensitive to tipifarnib when compared to control groups." (PMID 34771475, 2021). "The basal tumor cluster #3 demonstrated transcriptional downregulation of HRAS; cell dormancy; and a higher expression of IGFBP7, MDK, and B2M, recapitulating those of the tipifarnib-resistant (or cluster B) BC159-T#3 PDX tumor cells." (PMID 32460812, 2020). "Mutations of HRAS, FGFR3, PIK3CA and TERT were found in 2.9%, 27.2%, 14.9% and 76.7% of tumor samples, respectively." (PMID 33024200, 2020).
tumor (continued). "Here, we used scRNA-seq to depict the tumor landscape of a single case of chemo-resistant metastatic, muscle-invasive urothelial bladder cancer (MIUBC) addicted to an activating Harvey rat sarcoma viral oncogene homolog (HRAS) mutation." (PMID 32460812, 2020). "Tumor cells in the PDX that survived tipifarnib treatment showed a significant downregulation of HRAS as well as RAS and MAPK signaling-related genes." (PMID 32460812, 2020). "When HRAS activation was pharmacologically inhibited by tipifarnib (50 mg/kg, oral, twice a day), tumor growth was significantly suppressed and HRAS-mediated ERK and AKT activation was reduced." (PMID 32460812, 2020). "Suppressed HRAS-mediated signaling by tipifarnib in each tumor cell was also confirmed at the protein level by single-cell Western blotting." (PMID 32460812, 2020). "Previous report confirmed that AZD8055 exhibited an obvious tumor-inhibition effect in HRAS mutant or BRAF mutant PTC cells induced xenograft models." (PMID 32284745, 2020). "We found that the expression of HRAS was upregulated in RCC cells that stably overexpressed QPCT, as well as in the xenograft tumours, while the expression of HRAS was downregulated when QPCT was knocked down in RCC cells." (PMID 31534544, 2019). "Transforming growth factor β (TGFβ) cooperates with HRAS to promote epithelial-mesenchymal transition (EMT) process that contributes to tumor invasion and metastasis." (PMID 30655611, 2019). "Other variants detected in this tumor, such as those inFGFR3,PDGFRA,KDR (c.1416A>T),CSF1R,EGFR,RET,HRAS,PIK3CA,FLT3 (c.1310-3T>C), andSMAD4, are benign." (PMID 32612806, 2019). "Related literature reports found that HRAS was involved in the activation of multiple signalling pathways in tumours." (PMID 31534544, 2019). "In this sense, we evaluated the prognostic value of the ZNF611, ZNF304, RIPK1, TNFRSF21, DUSP8 and HRAS genes according to tumor subtypes." (PMID 30938061, 2019). "HRAS belongs to the Ras oncogene family, and HRAS mutants are known to aberrantly activate mTOR signalling in HNSCC tumours." (PMID 30970654, 2019). "Investigations in the zebrafish model further showed disruption of ubtor gene upregulated the mTOR signaling and promoted HRAS(G12V) mediated tumor formation in intact animals." (PMID 30080879, 2018). "HRAS(G12V), a dominant-active form of human oncogene HRAS, can promote tumor formation when overexpressed in zebrafish embryos." (PMID 30080879, 2018). "Intriguingly, some of these molecules are related to oncogenesis and tumour progression/metastasis, namely, HRAS, KRAS, TGFBR1, TGFBR2, RB1, ITGA6, ITGB4, mTOR, TSC2 and APLP2." (PMID 30258067, 2018). "Cluster 2 contains tumours with mutations in RET, TMEM127, MAX, NF1 and HRAS and is characterized by aberrant activation of kinase signalling pathways." (PMID 28327598, 2017). "There was significant correlation between HRAS mRNA expression and tumor thickness; higher HRAS mRNA level was correlated with higher tumor thickness (p = 0.002)." (PMID 29349077, 2017). "Of the 11 SpTs in which FGFR3/HRAS/NRAS mutations have been identified so far, chromosomal copy number information is available for only one tumor (SS2) from an 84 year old man." (PMID 28542371, 2017). "Three members of the GTPases of the RAS family, KRAS, HRAS and NRAS, are well known for their ability to cause neoplasia." (PMID 27857191, 2016).
tumor (continued). "HRAS was down-regulated in neighbouring and tumour tissue compared to the normal mucosa, while NRAS seemed to be equally down-regulated in neighbouring and up-regulated in tumour tissue." (PMID 27465361, 2016). "PLA2G16 is reported to suppress HRAS induced transformation, and inhibit cell proliferation, colony formation, and promote apoptosis, and was considered as a tumor suppressor before its phospholipase activity was discovered." (PMID 26933804, 2016). "The comparison of the genetic characteristics of muscle-invasive and non-invasive tumours revealed that non-invasive tumours over-express HRAS and FGFR3 or produce highly activated forms of these proteins." (PMID 25569276, 2015). "We previously demonstrated that the C118S mutation reduced the ability of wild-type HRAS to be activated in an eNOS-dependent fashion and to promote oncogenic KRAS-driven tumor growth." (PMID 25902334, 2015). "PIK3CA, HRAS and AKT1 (all n = 1) mutations were detected in FFPE tumor specimens, while NRAS, PIK3CA and AKT1 (all n = 1) mutations were found in cpDNA samples." (PMID 23144797, 2012). "In the EP group, 12 tumours had pathogenic mutations in key genes associated with response to anti‐EGFR therapy (1 × in BRAF + PTEN, 1 × in BRAF + PIK3CA, 2 × in BRAF, 3 × in PTEN, 2 × in NRAS, 1 × in KRAS, 1 × in HRAS and 1 × in PIK3CA)." (PMID 40302146, 2025). "We then assessed the relationships between genomic subtypes and clinical characteristics and found that genomic subtypes were significantly associated with T stage, tumor grade, and EORTC scores, with a gradual escalation observed among the FGFR3/HRAS, FGFR3 & chr9Del, GI, and AA-like subtypes." (PMID 40247187, 2025). "Of note, in the studied family we detected a somatic HRAS mutation in the proband tumor samples, but that alteration was not present in the other elements." (PMID 38338801, 2024). "The two groups were compared for variables of age, gender, tumor location, histology, depth of tumor invasion, lymph node metastasis, lymph invasion, venous invasion, distant metastasis, CEA level, and KRAS, NRAS, and HRAS mutations." (PMID 37758931, 2023). "We also found that G6PD, NRAS and HRAS may have a positively moderate correlation with most of IGCs in Tumor cell/APC/DC group than in T cell group." (PMID 37143953, 2023). "Most BA/CMPT cases have been reported from Japan and other Asian countries and may involve genetic mutations of BRAF, EGFR, KRAS, HRAS, and ALK; thus, the tumor is viewed as an oncological disease." (PMID 39517003, 2023). "According to our evidence, HRAS overexpression can be found in about 40% of GEP-NET tumor tissues and might portend a higher sensitivity to lenvatinib treatment." (PMID 36743926, 2022). "In this study, mutations in the genes ARID1A, APC, ERBB4, NCOR1, PDGFRA, ATM, and CDKN2A were either non-recurrent or of very low frequency, while none of the 14 sequenced EP tumours harboured mutations in the genes HRAS, EGFR, or RB1." (PMID 34045664, 2022). "Of the six responder patients, four showed HRAS overexpression in the tumor tissue." (PMID 36743926, 2022). "PLD1 is a critical downstream mediator of HRAS‐induced tumour formation." (PMID 35775110, 2022). "Therefore, their transformation by hRas requires either a cooperating oncogene or the inactivation of a tumor suppressor." (PMID 35361222, 2022).
tumor (continued). "Specifically, GRP78 and HRAS can both contribute to tumour immune escape." (PMID 34943819, 2021). "Tipifarnib was highly active in the HRAS mutant setting and displayed weak activity in the majority of HRAS wild-type models, but we observed unexpectedly robust inhibition of tumor growth in a minority of HRAS wild-type cases, all of which expressed high levels of the HRAS gene." (PMID 34771475, 2021). "On the other hand, HRAS mRNA in tumor was overexpressed in adenocarcinoma." (PMID 33549031, 2021). "From 1979, cellular ras sequences with transforming properties were identified by transfection of tumor DNA initially by Robert Weinberg from rodent tumors, and the isolation of homologous oncogenes from human tumors soon followed, including HRAS and KRAS, and a new member of the family named NRAS." (PMID 32728828, 2020). "However, as a single agent, tipifarnib appears to have modest clinical effects in tumors that are driven through oncogenic HRAS function; these are insufficient to induce long-term tumor inhibition because of the complexities of HRAS." (PMID 32460812, 2020). "In addition, SAP18 overexpression in WT tumor-bearing mice markedly decreased the expression of HRAS and PI3Kγ and the expression of HRAS and PI3Kγ was closely connected with ERK1/2 activation." (PMID 31395859, 2019). "HRAS and KRAS mutations have been identified in up to 50% of human UPS tumours." (PMID 29731980, 2018). "However, studies using transgenic mouse models have shown that when its overexpression is combined with other oncogenic mutations like HRAS or C-NEU, it accelerates tumor growth." (PMID 29416040, 2018). "Erastin is another anti-tumor agent that use VDAC as a docking site in mitochondria and induces oxidative, non-apoptotic death in human tumor cells with mutations in the oncogenes HRAS, KRAS, or BRAF." (PMID 29682501, 2018). "Since MDA-MB-231 and SUM-159 have activating mutations in KRAS and HRAS respectively, it is possible that GADD45A could be functioning as a tumor suppressor in these cell lines." (PMID 28235006, 2017). "Although the sig-pos-AFD enriched genes are largely tumor suppressive, HRAS and ERBB2, which are as well-known canonical oncogenes, are observed to be significantly enriched with sig-pos-AFD missense mutations (P value of 2.37 × 10−09 in HNSC and 9.03 × 10−4 in STAD, respectively)." (PMID 28490743, 2017). "As a positive control, HRAS KO almost completely prevented tumor growth, indicating that cells escaping gene KO, which are positively selected during tumor growth, are only a small fraction of the injected cells and do not significantly reduce the dynamic range of detectable differences." (PMID 29327641, 2017). "C2A tumours are mainly driven by RET, NF1 and HRAS mutations." (PMID 25625332, 2015). "We investigated the relationships between HRAS mutation and tumour location and presence or absence of an inherited PCC/PGL/HNPGL gene mutation." (PMID 25883647, 2015). "Thus, we used immunohistochemical markers to enable histological identification of the type of tumor induced by subcutaneous injection of the HRAS, c-Myc and shp53 oncogenes in female C57BL/6 mice." (PMID 23380875, 2013).
tumor (continued). "We speculated that rs12628 and rs112587690 polymorphisms might have a potential influence on transcriptional regulation of HRAS gene, and thus we sought to examine the level of HRAS mRNA in the tumor tissues according to rs12628 and rs112587690 genotypes." (PMID 22618666, 2012). "An important question is whether MAP2K1-driven tumours align with conventional WHO melanomagenesis pathways, alongside BRAF, NRAS, and NF1 mutations, or pathway IV (Spitz), alongside kinase gene fusions and HRAS mutations." (PMID 40107205, 2025). "HRAS-mutant cell line derived xenograft models also exhibited tumour regression, irrespective of the mutation introduced, however WT mice did not, indicating its effects are restricted to oncogenic HRAS, potentially through reduction in angiogenesis and cell cycling." (PMID 39372214, 2024). "None of the analyzed tumor samples resulted mutated for HRAS." (PMID 36743926, 2022). "HRAS-mutant models tumors regrew after cessation of exposure to tipifarnib, with mild tumor regression on retreatment, indicating that FTase inhibition may confer only a cytostatic effect on tumor growth." (PMID 35459782, 2022). "The xenograft SJRHB000026 (HRAS G13R, PIK3CA missense mutation) had less profound tumor growth inhibition compared to other HRAS-mutant xenografts, which may be at least in part due to the concomitant PIK3CA mutation and the emergence of early adaptive or acquired resistance." (PMID 35459782, 2022). "Moreover, HRAS is able to regulate the chemotaxis of some immune cells at the tumour stroma." (PMID 34943819, 2021). "HRAS and BRAF mutation allele frequencies (range 11–46%; mean 29%) were consistent with somatically acquired mutations (i.e., admixed with normal stroma), which we confirmed in three CAA cases by laser microdissection (and PCR/Sanger sequencing) of separate tumor epithelium and stroma." (PMID 30741938, 2019). "For instance, it has been clarified that ligands of VDAC proteins selectively induce non-apoptotic cell death in tumor cells harbouring mutations in the oncogenes HRAS, KRAS, or BRAF by comparing the binding proteins of erastin A6 and erastin B2, an erastin analogue that lacks its activity." (PMID 23431365, 2013). "We speculated that rs12628 and rs112587690 polymorphisms could have a potential influence on transcriptional regulation of HRAS gene, thus we sought to examine the level of HRAS mRNA in tumor tissues according to the different genotypes of rs12628 and rs112587690 polymorphisms." (PMID 22618666, 2012). "PDGFRA activation leads to phosphorylation of PIK3R1, triggering downstream signaling cascades including calcium mobilization and activation of PKC, AKT1, HRAS/MAPK/ ERK, and STAT pathways, thereby promoting tumor growth and survival." (PMID 41426972, 2025). "HRAS and SMAD2 were reported to promote EMT in tumor cells, but the mechanism of the interaction between these 2 proteins is not clear." (PMID 39913299, 2025).